DES (desmin)
Diseases named in the same sentence as DES in open-access papers (continued):
Sharing a sentence is not in itself a finding about the gene and the disease.
myopathies (93 papers, 2007 to 2025). "We describe a case of a 24-year-old female diagnosed with desmin-related myopathy due to a heterozygous pathogenic NM_001927.4 (DES):c.1216C>T, p.Arg406Trp variant." (PMID 40606663, 2025). "Emergence of cardiac dysfunction in desmin-related myofibrillar myopathies has been associated with sarcomeric disorganization and mitochondrial abnormalities in cardiomyocytes." (PMID 38167524, 2024). "Mutations in desmin cause myofibrillar misalignment, mitochondrial dysfunction, and impaired mechanical integrity leading to myopathies, often characterized by the accumulation of protein aggregates." (PMID 38566246, 2024). "Mutations in the desmin gene (i.e., C333S mutation) lead to the accumulation of granulo-filamentous desmin-positive aggregates and myopathy, which can be reduced by antioxidant treatment by up to 75%." (PMID 39594525, 2024). "Some of the findings discussed in this article suggest that certain histological patterns of skeletal muscle tissue associated with the CCT5 Leu224Val mutation are similar to those found in desmin-related myopathies (DRMs) and in α-crystallinopathy." (PMID 37237456, 2023). "In particular, substitution of R120 for glycine (hereon designated as CRYABR120G) was identified as a causal mutation in Desmin related myopathy characterized by intracellular accumulation of spheroid inclusion bodies consisted of Desmin." (PMID 37435054, 2023). "The localization pattern of HSPB5 in the ER region was similar to that of the HSPB5 (R120G) mutant, which causes familial desmin-related myopathies." (PMID 36232565, 2022). "HSPB5-knockout mice exhibit severe progressive myopathy with aging, and a point mutation, HSPB5 (R120G), has also been reported to cause desmin-related myopathy in humans." (PMID 36232565, 2022). "Desmin is a critical component in the myofiber network, and various myopathies are associated with its disruption and aggregation." (PMID 35878184, 2022). "With respect to myofibrillar myopathy-associated proteins, alpha-crystallin B, desmin, myotilin, BAG family molecular chaperone regulator 3, and heat shock protein beta-8 showed enhanced expression in type I and type IIa fibers." (PMID 34201234, 2021). "Among them is the intermediate filament protein desmin, which is mutated in myopathy and several RNA-binding proteins such as FUS or C1QBP that are involved in disease." (PMID 34943834, 2021). "Mutations of desmin are associated with myofibrilar myopathies, a heterologous group of myopathies primarily affecting Z-disc organisation." (PMID 34831284, 2021). "In contrast, the destabilized R120G mutant of αBc, which causes desmin-related myopathy, also has an increase in size as observed for αBc:DAox but has significantly reduced chaperone ability." (PMID 33918165, 2021). "Ablation of either β- or γ-actin specifically in skeletal muscle causes mild progressive myopathies, and loss of desmin causes disruptions of muscle architecture." (PMID 31218456, 2019). "The most-studied mutation, R120G, resides within the α-crystallin domain and is associated with desmin-related myopathy." (PMID 30475834, 2018). "The desmin network is recognized as a key mechanical element that can become progressively dysfunctional through myopathy-causing desmin mutations." (PMID 28470624, 2017). "Cytosolic heterogeneous multiprotein aggregation and mitochondrial abnormalities characterize myopathies caused by human mutations in desmin or CRYAB (reviewed in." (PMID 28470624, 2017). "Our data suggest that mutated desmin already markedly impedes myocyte structure and function at pre-symptomatic stages of myofibrillar myopathies." (PMID 28469177, 2017). "Our study demonstrates that EBS-MD causing PLEC mutations universally result in a desmin protein aggregate myopathy phenotype despite marked differences in individual plectin protein expression patterns." (PMID 27121971, 2016).
myopathies (continued). "Whole exome sequencing identified a known pathogenic p.S13F mutation in DES that had previously been associated with desmin-related myopathy." (PMID 26097489, 2015). "Our results highlight the heterogeneous pathogenic mechanisms between different desmin mutants and open the way for new advances in the study of myofibrillar myopathies." (PMID 23425003, 2013). "All markers were detectable in GNE myopathy and the highest mean values of expression were noted for the degeneration-/cell stress associated markers αB-crystallin (1.052), desmin (0.315), ubiquitin (0.263), and APP (0.0226)." (PMID 23496965, 2013). "We also demonstrated that the R120G knock-in mice develop myopathy, weakness, loss of αB-crystallin solubility, and an increase in desmin-αB-crystallin aggregates in muscle tissue." (PMID 21445271, 2011). "It is therefore important to identify the sequences in αB-crystallin that are responsible for the effects on intermediate filaments and particularly desmin because mutations in either can be the genetic basis of myopathy." (PMID 22096479, 2011). "Compare these data to the detailed analysis of the Q151X myopathy-causing mutation in αB-crystallin where increased desmin cosedimentation of Q151X αB-crystallin was accompanied by a very significant decrease in desmin filament-filament associations." (PMID 22096479, 2011). "The R120G mutation of αB-crystallin is known to cause desmin-related myopathy, but the mechanisms underlying the formation of cataract are not clearly established." (PMID 18618007, 2008). "Many congenital cataract crystallin genes have been reported; the R120G αB-crystallin causes desmin-related myopathy and cataract." (PMID 17615546, 2007). "Given desmin's crucial role in structural integrity, preventing muscle wasting and its association with mitochondrial dysfunction and impaired ATP‐dependent contraction in myopathies, we assessed mitochondrial function in Asb2 MKO muscle." (PMID 40641155, 2025). "Additionally, this report describes the first documented case of desmin-related myopathy caused by inheritance of this mosaic pathogenic DES variant." (PMID 40606663, 2025). "The interactions, confirmed also by GST pull-down assays, indicating the necessity of the desmin head domain and, furthermore, point out its role in function of mitochondria and lysosomes, organelles which are disrupted in myopathies due to desmin head domain mutations." (PMID 38607042, 2024). "Desmin, as a major component of intermediate filaments specifically expressed in smooth, skeletal, and cardiac muscles, presents some mutations associated to muscle defects and myopathies." (PMID 36453730, 2022). "Diverse mutants of the desmin gene are associated with myopathy and cardiopathy." (PMID 35720129, 2022). "For instance, mutations in desmin, the main protein of the cytoskeleton intermediate filament component, cause a class of myopathies, and a larger elevation of basal [Ca2+]mit after repeated contractions has been observed in skeletal muscle fibers of a transgenic mouse model of desmin myopathy." (PMID 36479146, 2022). "For example, mutations in desmin encoding gene (DES) were reported in association with myopathies in both skeletal and cardiac muscles leading to the development of in vitro and in vivo tools to widely investigate these mutations including the novel variants and their clinical impact." (PMID 33567613, 2021). "Desmin and dystrophin-related myopathies are often associated with debilitating dysfunction and myopathy is compounded in desmin and dystrophin double-knockout mice, which manifest a remarkable dystrophic phenotype with profound deterioration of sarcomere organisation and Z-line alignment." (PMID 34067869, 2021). "In addition, missense variants in the desmin gene have been identified in several families with desmin-related myopathy and presenting RCM." (PMID 29367558, 2016).
myopathies (continued). "However, subsequent studies reported the association between desmin mutations and limb girdle, scapuloperoneal, and generalized myopathy phenotypes." (PMID 23143191, 2013). "The discovery that the R120G mutation in αB-crystallin (CRYAB, HSPB5) phenocopies desmin mutations in human desmin-related myopathies (DRMs) provided the first genetic evidence in support of the proposed functional interaction between CRYAB and intermediate filaments." (PMID 23530264, 2013). "Homozygous null mutation of desmin or CRYAB only induces very mild myopathy compared to myopathy induced by mutated αB-crystallin (R120G), indicating that the toxicity may be induced by aggregation itself." (PMID 21423662, 2011). "Thus, the desmin aggregation occurring in myofibrillar myopathy attributable to mutations in αB-crystallin is due to the loss of its chaperone function." (PMID 21423662, 2011). "Both hetero‐ and homozygous R405W desmin knock‐in mice showed classical myopathological features of a myofibrillar myopathy with desmin‐positive protein aggregation, degenerative changes of the myofibrillar apparatus and mitochondrial alterations." (PMID 41165044, 2025). "The present study demonstrates that the expression of mutant desmin results in a myofibrillar myopathy in hetero‐ and homozygous R405W desmin knock‐in mice." (PMID 41165044, 2025). "Our study demonstrates that the expression of R405W mutant desmin leads to a myofibrillar myopathy in hetero‐ and homozygous R405W desmin knock‐in mice." (PMID 41165044, 2025). "The classical morphological hallmarks of the clinically and genetically diverse group of human myofibrillar myopathies are signs of myofibrillar degeneration and desmin‐positive protein aggregates." (PMID 40947309, 2025). "An important phenomenon complicating genetic diagnostics, not only in desmin-related myopathy but in many genetic conditions, is mosaicism." (PMID 40606663, 2025). "In this report, we describe a case of a young woman diagnosed with desmin-related myopathy after genetic testing." (PMID 40606663, 2025). "We report the first documented case of mosaic carriership of a pathogenic DES variant in an asymptomatic individual and subsequent inheritance by the offspring, leading to desmin-related myopathy." (PMID 40606663, 2025). "Irrespective of the individual gene defect, the striated muscle pathology of myofibrillar myopathies is characterised by desmin‐positive sarcoplasmic and subsarcolemmal protein aggregates and degenerative changes of the myofibrillar apparatus." (PMID 40947309, 2025). "The heterozygous state of the c.1216C>T variant was confirmed through Sanger sequencing, and a diagnosis of desmin-related myopathy was concluded, consistent with the patient’s physical complaints." (PMID 40606663, 2025). "A muscle biopsy from one twin showed pathological features consistent with a diagnosis of myofibrillar myopathy, including fiber disarray and desmin accumulation." (PMID 41409743, 2025). "Several genes were found to be significantly enriched by simvastatin treatment in primary human muscle cells and were mapped to both OMIM as well as KEGG pathways for myopathy, including DES, TNNT1, MYH7, and DYSF." (PMID 40149400, 2025). "Muscular reactive oxygen species (ROS), caspase-3, and desmin immunostaining were used to determine myopathy." (PMID 39356321, 2024). "This is demonstrated by the attenuation of MetS-induced myopathy by vitamin D3, decreased oxidative stress, increased desmin immuno-expression, and caspase-3 activity." (PMID 39356321, 2024). "Muscle cells were found in histology to be consistent with myofibrillar myopathy with aggregates staining positive for desmin and CRYAB, although the morphology of the aggregates in electron microscopy is different than those reported for CRYABR120G mutations." (PMID 38474073, 2024).
myopathies (continued). "The crucial roles of IFs in physiology is further supported by the discovery of a wide aggregation of IF proteins in numerous pathologies, including desmin bodies in myopathies and NF accumulation in most neurodegenerative diseases." (PMID 38164457, 2023). "In patient one, muscle biopsy indicated vacuolar myopathic changes and atypical pathological changes of myofibrillar myopathy characterized by desmin deposits, Z‐disc disorganization, and electronic dense granulofilamentous aggregation." (PMID 34978387, 2022). "Expression of p.R406W mutant desmin, identified in patients with desmin-related myopathy, modified focal adhesion area and expression of adhesion-signaling genes in myogenic C2C12 cells." (PMID 35350386, 2022). "Our results are consistent with the moderate myopathy seen in desmin-null muscles and support the idea that desmin contributes significantly to sarcolemmal stability and lateral force transmission." (PMID 34489727, 2021). "The phenotype of the desmin-null mice and those of the mdx and synemin-null mice, studied earlier, are consistent with the severity of the myopathies seen in these animals." (PMID 34489727, 2021). "Based on the myopathology characterized by desmin accumulation, the disease was described as a desmin-related myopathy and is now classified in the Online Mendelian Inheritance in Man (OMIM) database as myofibrillar myopathy 2 (MFM2, MIM #608810)." (PMID 32093037, 2020). "The muscular phenotype of the Drp/MC mice resembles that observed in the central core disease, characterised by core areas without COX activity, and the myofibrillar myopathy characterised by desmin accumulation and aggregation." (PMID 32042098, 2020). "The disorganization of desmin often resembled the pattern seen in myofibrillar myopathies where the primary clinical feature is progressive muscle weakness." (PMID 30764835, 2019). "Mutations in the Des gene coding for the muscle-specific intermediate filament protein desmin lead to myopathies and cardiomyopathies." (PMID 31341183, 2019). "Similar to the results of desmin knockout mice models, only homozygous desL114F/L114F mice showed an earlier onset myopathy phenotype." (PMID 31835587, 2019). "We suggest that the capability of CRYAB to distinguish between filaments with different surface topologies due either to mutation (R454W) or assembly protocol is important to understanding the pathomechanism(s) of desmin-CRYAB myopathies." (PMID 28470624, 2017). "Beyond a more central position of myonuclei - a typical morphological sign in a wide variety of myopathies - these data demonstrate that the expression of mutant desmin also inflicts a nuclear pathology." (PMID 28469177, 2017). "Firstly, we collected the frozen sections of the left biceps of patients with desmin-related myopathy, then analyze by using routine staining and immunohistochemical staining." (PMID 27941998, 2016). "Our study demonstrates that EBS-MD causing PLEC mutations, though leading to marked differences in the individual plectin protein expression pattern, all result in a desmin protein aggregate myopathy phenotype." (PMID 27121971, 2016). "Furtherly, we present the understanding of desmin related myopathies by studying the mitochondrial apoptotic proteins." (PMID 27941998, 2016). "Recognition that mitochondrial dysfunction occurs in desmin-related myopathy clarifies the basis for the multi-systemic manifestations, as are typical of primary mitochondrial disorders." (PMID 26097489, 2015). "Understanding the mitochondrial pathophysiology of desmin-related myopathy highlights the possibility of new therapies for this otherwise untreatable and often fatal class of disease." (PMID 26097489, 2015). "This is reminiscent of the situation in desmin related myopathies where the characteristic histopathological feature of the disease is protein aggregates containing both αB-crystallin and desmin." (PMID 22096479, 2011).
myopathies (continued). "In humans, and perhaps also in mice, the promotion of desmin filament aggregation by αB-R120G mutant protein may be repressed at a young age by the expression of competing wild-type αB-crystallin, which could explain the late onset of myopathies caused by αB-crystallin mutations." (PMID 21445271, 2011). "αB-R120G heterozygous and homozygous mutant mice recapitulate many of the pathologic features observed in DRM patients, including myopathy, desmin aggregates, and mitochondrial pathology." (PMID 21445271, 2011). "This important observation is relevant not only to the formation of the protein aggregates that contain both desmin and αB-crystallin and typify desmin related myopathies, but also to the interaction of αB-crystallin with other filamentous protein polymers." (PMID 22096479, 2011). "Out of the known list of myofibrillar myopathy–related genes, only the protein quality control related candidates Dnajb6 and Bag3 were significantly up‐regulated in soleus muscle from both hetero‐ and homozygous R405W desmin mice at three months of age." (PMID 41165044, 2025). "The immunofluorescence and ultrastructural analyses depicted the pathognomic features of myofibrillar myopathies [S22] comprising desmin‐positive protein aggregates, degenerative changes of the myofibrillar apparatus, vacuolar structures and mitochondrial abnormalities." (PMID 41165044, 2025). "To study the molecular pathophysiology of this protein aggregate myopathy in more detail, we next analyzed the ribosomal translation of R405W/R406W desmin and the global, R405W desmin‐induced changes on the RNA and protein levels by transcriptomics and proteomics." (PMID 41165044, 2025). "Furthermore, BAG3 mutations can cause myofibrillar myopathies and cardiomyopathy, in which accumulation of BAG3 or myofibrillar proteins, e.g., myotilin, desmin, and αB-crystallin, can be found." (PMID 39012547, 2024). "Interestingly, BAG3 or αB-crystallin aggregation as well as aggregation of myofibrillar structural proteins like myotilin and desmin in the Ku + biopsies resemble aggregation in myofibrillar myopathies." (PMID 39012547, 2024). "Although muscle fibers can develop in the absence of desmin, defects in the genes encoding this protein result in severe myopathy." (PMID 38732204, 2024). "Thus, mutations in IF genes have been shown to cause a wide range of >80 tissue-specific diseases, from skin diseases (keratin), myopathies (desmin), cataract (Bfsp) to neuropathies (NFs, GFAP)." (PMID 38164457, 2023). "Overall, the SM myopathy had only a minor impact on the myofibrillar proteins profiles and did not affect either free calcium concentration, calpain activity, or the degradation of desmin and TnT, while storage time strongly affected all the traits measured." (PMID 35784896, 2022). "Vinculin expression was also increased in desmin-related myopathy patient muscles." (PMID 35350386, 2022). "We first identified the usual suspects of cellular mechanics (actin network, acto-myosin contractility, and CC adhesion) as being fundamental in tissue surface tension and elasticity, but our approach was also used on a cellular model of desmin-related myopathies." (PMID 36453730, 2022). "HSPB5 (R120G) mutant, which causes desmin-related myopathy, presented no cytoprotective effect of HSPB5." (PMID 36232565, 2022). "Desmin forms intermediate filaments involved in the muscle cell architecture by anchoring several structures (nucleus, mitochondria, Z-disc) to the plasma membrane at the costamers, and alterations in desmin result in myopathies." (PMID 33176865, 2020). "Possibly, in vitro exposure of muscle cell lines to sesquiterpene lactones could be used in the initial screening and experimentation to elucidate aspects of desmin-related myopathies in humans or the quest to find potential and more targeted therapies." (PMID 32708381, 2020).